MRGPRX2 (MAS related GPR family member X2)
Diseases named in the same sentence as MRGPRX2 in open-access papers (continued):
Sharing a sentence is not in itself a finding about the gene and the disease.
rheumatoid arthritis (2 papers, 2024). A chronic, systemic autoimmune disorder characterized by inflammation in the synovial membranes and articular surfaces. "SH triggers drug-like allergic reactions while treating rheumatoid arthritis and triggers allergic reactions via MRGPRX2-mediated mast cell activation." (PMID 39144634, 2024). "Here, we show that degranulation of mast cells in inflammatory synovial tissues of patients with rheumatoid arthritis (RA) is induced via MAS-related G protein-coupled receptor X2 (MRGPRX2), and the expression of MHC class II and costimulatory molecules on mast cells are upregulated." (PMID 38168103, 2024).
skin reaction (2 papers, 2021 to 2024). "In the case of an adverse event to a routine SPT, where there is typically a skin reaction mediated by IgE (with results reported as positive or negative), it is possible that MRGPRX2 has an underlying role in these reactions." (PMID 38968527, 2024). "The data presented herein provide the first demonstration that irritating concentrations of rocuronium that were reported to induce skin reactions in patients with drug hypersensitivity induce degranulation in LAD2 cells, MRGPRX2-expressing RBL-2H3 cells and primary human skin MCs." (PMID 33467419, 2021).
autism spectrum disorder (1 paper, 2021). A spectrum of developmental disorders that includes autism, and Asperger syndrome. "MRGPRX2 is a receptor with multiple neuropeptide ligands, including cortistatin-14, and this receptor’s role was noted in a review of molecular mechanisms of autism spectrum disorder." (PMID 33834688, 2021).
COVID-19 (1 paper, 2022). A disease caused by infection with severe acute respiratory syndrome coronavirus 2. "Further studies are needed to improve the accuracy and sensitivity of allergen testing, including increased detection of the possible compounds of COVID-19 vaccines (such as tromethamine, EDTA, or spike protein), dosage adjustment, or increased additional cell markers (e.g., MRGPRX2)." (PMID 35740283, 2022). "However, no convincing evidence has demonstrated that MRGPRX2 or complements are involved in COVID-19-vaccine-induced immediate hypersensitivity reactions." (PMID 35740283, 2022).
eczema (1 paper, 2021). "Evidence is accumulating that MRGPRX2 may be crucial in the context of skin diseases, including eczema." (PMID 33429916, 2021).
fungal infection (1 paper, 2019). "In addition to fungal infection, MCs contribute to host defense against bacterial infection likely via MRGPRX2 and Mrgprb2." (PMID 30987258, 2019).
glioblastoma (1 paper, 2025). The most malignant astrocytic tumor (WHO grade IV). "Initial hit compound characterization confirmed MRGPRX2-blocking activity in an orthogonal assay measuring inhibition of Gq protein-mediated calcium mobilization in a different cell line, an MRGPRX2-overexpressing glioblastoma cell line (LN229)." (PMID 40254631, 2025).
interstitial cystitis (1 paper, 2025). A rare chronic debilitating urogenital disease characterized by urinary frequency, urgency, and pelvic pain. "In murine models of interstitial cystitis/bladder pain syndrome (IC/BPS), MrgprB2-dependent mast cell–neuron circuits promote bladder inflammation and colonic hypersensitivity; MRGPRX2 antagonism reduces these effects in humanized mice." (PMID 40948761, 2025).
ischemic stroke (1 paper, 2025). A stroke disorder caused by obstruction of blood flow to the brain, due to thrombotic (local blood clot formation) or embolic (due to a blood clot or other material traveling from another site) event. "In addition to describing the role of Mrgprb2 in mouse ischemic stroke, we discover that MRGPRX2, the human ortholog of this mast cell receptor, is expressed in human dural mast cells." (PMID 40712576, 2025).
non-small cell lung carcinoma (1 paper, 2022). A group of at least three distinct histological types of lung cancer, including non-small cell squamous cell carcinoma, adenocarcinoma, and large cell carcinoma. "Our findings may have relevance to TKI-induced DHRs mediated by MRGPRX2, future studies are warranted to characterize other TKIs such as crizotinib, which is used to treat metastatic non-small cell lung cancer." (PMID 36341461, 2022).
Opportunistic infection (1 paper, 2021). An infection that is caused by a pathogen that would generally not be able to cause an infection in a host with a normal immune system. "We believe that the therapeutic effect of MRGPRX2 inhibition can be exploited to the maximum extent by lowering the risk of opportunistic infections." (PMID 34831128, 2021). "Therefore, MRGPRX2 inhibition may pose risks such as opportunistic infections." (PMID 34831128, 2021).
Shock (1 paper, 2020). The state in which profound and widespread reduction of effective tissue perfusion leads first to reversible, and then if prolonged, to irreversible cellular injury. "Surprisingly, no therapeutic drugs are available which can directly target MRGPRX2 for treatment of anaphylactoid shock." (PMID 32106575, 2020).
skin infection (1 paper, 2021). An inflammatory process affecting the skin, caused by bacteria, viruses, parasites, or fungi. "Because human skin MCs express MRGPRX2 at high levels, these findings suggest that murepavadin can be utilized for treating P. aeruginosa skin infection through harnessing MC’s host defense and wound healing properties." (PMID 34248979, 2021).
Stroke (1 paper, 2025). Sudden impairment of blood flow to a part of the brain due to occlusion or rupture of an artery to the brain. "After determining that Mrgprb2 and MRGPRX2 are key mast cell receptors activated after stroke, we next asked which ligand(s) might underlie its activity." (PMID 40712576, 2025). "We have identified MRGPRX2 as a specific target to address post-stroke inflammation, by directly inhibiting the significant mast cell activity that drives the skull bone-dura-brain axis of inflammation." (PMID 40712576, 2025). "MRGPRX2−/− and WT mast cells show similar reactivity to serum from healthy patients, suggesting that MRGPRX2 is uniquely sensing a factor present in stroke serum." (PMID 40712576, 2025). "Taken together, we show that human dural mast cells are activated after stroke, and that this activation is in part dependent on SP-mediated activation of MRGPRX2." (PMID 40712576, 2025). "We additionally collected post-mortem brain tissue from stroke and non-stroke patients to assess for presence of MRGPRX2-mast cells." (PMID 40712576, 2025). "Further studies into age- and sex-matched analyses of stroke patients will be imperative to further support this role of MRGPRX2 in stroke." (PMID 40712576, 2025). "We demonstrate that the human ortholog, MRGPRX2, is expressed in human meningeal mast cells, and is activated by upregulation of the neuropeptide substance P in stroke." (PMID 40712576, 2025). "Via MRGPRX2, it is plausible that these drugs can activate dural mast cells and thus worsen inflammatory injury in stroke patients." (PMID 40712576, 2025). "To narrow down whether MRGPRX2 is responding to SP in the sera, we immuno-depleted both healthy and stroke serum of SP by pre-incubating the sera with anti-SP antibodies." (PMID 40712576, 2025). "Moreover, we demonstrate that these human mast cells are activated in response to stroke, and that this activation is in part driven by substance P, a known ligand of MRGPRX2." (PMID 40712576, 2025). "While MRGPRX2 activation may be harmful in stroke patients, inhibition of MRGPRX2 instead may provide robust benefits." (PMID 40712576, 2025). "Neuropeptide substance P is a ligand for Mrgprb2 and MRGPRX2 activation in stroke." (PMID 40712576, 2025). "Thus, MRGPRX2 antagonists are promising potential therapeutic candidates for significantly attenuating post-stroke inflammation." (PMID 40712576, 2025). "We first collected dura from non-stroke patients undergoing elective craniotomies to determine whether mast cells are present in human dura and whether they express MRGPRX2." (PMID 40712576, 2025). "Therefore, we propose that MRGPRX2 may be a promising drug target in the long search for a therapeutic to combat post-stroke inflammation." (PMID 40712576, 2025). "Thus, we show here that osthole acts via a Mrgprb2-dependent manner to inhibit post-stroke inflammation and improve outcomes, providing evidence that perhaps inhibition of MRGPRX2 may be a promising therapeutic in combating post-stroke neuroinflammation in human patients." (PMID 40712576, 2025). "While there is an increase in GFAP in stroke brains as a marker of injury, there is no MRGPRX2 or tryptase expression, suggesting a lack of MRGPRX2-expressing mast cells in the human brain after stroke, consistent with our mouse data." (PMID 40712576, 2025). "Clearing SP from stroke serum significantly reduces its activation of WT but not MRGPRX2−/− LAD2 mast cells, pointing towards a specific SP-MRGPRX2 interaction." (PMID 40712576, 2025).
skin disorder (6 papers, 2018 to 2024). Any deviation from the normal structure or function of the skin or subcutaneous tissue that is manifested by a characteristic set of symptoms and signs. "As such, MRGPRX2 is attracting a great deal of attention as a putative drug target for the treatment of a variety of mast cell–driven pathologies, including disorders of the skin." (PMID 39493768, 2024). "Therefore, we sought to identify potent and selective antagonists to pharmacologically characterize the role of MRGPRX2 in relevant in vitro, ex vivo, and in vivo models to support further investigation of the role of this mast cell receptor in skin disorders." (PMID 39493768, 2024). "The relevance of overexpressed TSLP and deregulated MRGPRX2 activity in skin pathologies indicates that their synergy may have important ramifications for understanding and treatment of skin disorders, but also host-defenses organized by MRGPRX2 on the other end of the spectrum." (PMID 33429916, 2021). "However, there has been an explosion in interest in the role of non-IgE-mediated MC activation, in particular MRGPRX2, on drug-induced hypersensitivity and a variety of cutaneous disorders." (PMID 36275683, 2022). "The identification of MRGPRX2 on mast cells and the involvement of such receptors in SP-induced activation of human skin mast cells opens new opportunities for understanding pathomechanims of CSU and mast cell-mediated skin disorders and for exploring new therapeutic interventions." (PMID 30473632, 2018).
bacterial infections (5 papers, 2019 to 2024). "Together, these reports support the role for an Mrgprb2/MRGPRX2-mast cell axis in controlling bacterial infections at barrier surfaces." (PMID 38198852, 2024). "Mast cells sense bacterial infection when MRGPRX2/B2 binds quorum-sensing molecules (QSMs) secreted from bacteria or antimicrobial host defense peptides (HDPs) generated from infection-activated keratinocytes." (PMID 37296626, 2023). "The Mrgprb2/MRGPRX2-mast cell axis may go beyond responding to bacterial infections and could play a role in the host response to tick bites." (PMID 38198852, 2024). "In addition, our results provide a basis for the development of small peptides or peptidomimetics with MRGPRX2-agonistic activity as a targeted therapeutic intervention for the treatment of bacterial infections." (PMID 38184723, 2024). "MRGPRX2/B2 is involved in mast-cell-mediated host defense against bacterial infection." (PMID 37296626, 2023). "It is possible that these novel synthetic peptide mimetic MRGPRX2/Mrgprb2 agonists could form the basis of developing novel therapeutic agents for the treatment of drug-resistant fungal and bacterial infection via the harnessing of MCs’ immunomodulatory properties." (PMID 30987258, 2019). "Also, the mouse Mrgprb2 and human MRGPRX2 in MCs recognize Quorum-sensing molecules (QSMs) secreted by bacteria, which results in MCs eliciting antibacterial mediator release, suggesting MRGPRX2 is a potential therapeutic target for controlling bacterial infections." (PMID 33239034, 2020).
infection (3 papers, 2019 to 2025). The state of being infected such as from the introduction of a foreign agent such as serum, vaccine, antigenic substance or organism. "Tissue PAR-2 and MRGPRX2 expression was increased from pre-infection to 2 weeks post-infection followed by a gradual decrease until 20 weeks post-infection." (PMID 41325491, 2025). "Persistent stress and mild underlying infection is frequently evident in CSU and can activate mast cells via several neuropeptides and anti-microbial host defence proteins acting through the MRGPRX2." (PMID 31528163, 2019). "Additionally, some of the ligands for MRGPRX2, such as the cathelicidin LL-37 and the neuropeptide substance P, are produced by our own cells in response to infection and tissue injury." (PMID 32391014, 2020). "We observed upregulated expression of key non-histaminergic itch receptors PAR-2 and MRGPRX2, as well as the mediator tryptase, following infection." (PMID 41325491, 2025).
inflammation (3 papers, 2018 to 2021). Aberrant reaction of the microcirculation characterized by movement of fluid and leukocytes from the blood into extravascular tissues. "Furthermore, identification of gain and loss of function MRGPRX2 variants has important clinical implications for SP-mediated neurogenic inflammation and other chronic inflammatory diseases." (PMID 31652731, 2019).
immune disorders (1 paper, 2020). "Our findings will encourage researchers to study the MRGPRX2 pathway as well as novel drug development for non-IgE, mediated anaphylactoid shock and other immune disorders." (PMID 32106575, 2020).
MRGPRX2 also shares sentences with these, for which no sentence is quoted: allergic contact dermatitis (4 papers); chronic periodontitis (3); Arthritis (2); dermatitis (2); leukemia (2); acute pancreatitis (1); airway hyperresponsiveness (1); astrocytoma (1); cancer (1); fibrosis (1); food allergy (1); gout (1); metabolic disorders (1); mycosis fungoides (1); Osteopenia (1); osteoporosis (1); prurigo nodularis (1); Renal insufficiency (1); Sepsis (1).